NAT2 (N-acetyltransferase 2)
Diseases named in the same sentence as NAT2 in open-access papers (continued):
Sharing a sentence is not in itself a finding about the gene and the disease.
tuberculosis (continued). "NAT2 genotype-guided dosing stratification would improve early treatment success rates against tuberculosis, especially in highly-positive excretion levels of bacilli, if the high dose of INH was applied from the first prescription exclusively to rapid acetylators." (PMID 23150149, 2013). "Accordingly, this study aimed to investigate the potential association between NAT2 promoter methylation clinical parameters indicating ATDILI and to assess whether NAT2 promoter methylation could serve as a specific biomarker of ATDILI in tuberculosis patients." (PMID 40133601, 2025). "Specifically, a significant reduction in NAT2 demethylation index observed within 1–7 days of initiating tuberculosis treatment was found to be correlated with elevated serum aminotransferases detected within 8–60 days of starting treatment in tuberculosis patients." (PMID 40133601, 2025). "Finally, inhibition of (+)-1 toward NAT2 implies that it could be a structure template for developing NAT2 inhibitors with therapeutic potential in tuberculosis." (PMID 30037018, 2018). "TB patients were also reported to have relatively higher NAT2 expression levels in natural killer (NK) cells and monocytes as compared to healthy volunteers, suggesting its potential role as an early biomarker in the innate immune response to Mycobacterium tuberculosis." (PMID 40138446, 2025). "Considering lower NAT2 demethylation index as an independent determinant of ATDILI, we proceeded to investigate its effect on the occurrence of ATDILI in tuberculosis patients." (PMID 40133601, 2025). "In tuberculosis patients with ATDILI, NAT2 demethylation index was found to be significantly decreased when compared to healthy controls (P < 0.0001)." (PMID 40133601, 2025). "NAT2 SNPs and the slow acetylator phenotype have been implicated as risk factors for the development of antitubercular drug-induced liver injury (AT-DILI) in several tuberculosis (TB) populations." (PMID 40138446, 2025). "The present study investigated the distribution of the N-Acetyltransferase 2 (NAT2) genotype, isoniazid acetylation status, genotype-phenotype concordance of NAT2, and isoniazid plasma exposure among Ethiopian tuberculosis patients." (PMID 37454203, 2023). "PHASE accurately predicted the NAT2 acetylation phenotype in 92 of 93 samples (99%) from genotypic data in our mixed ancestry study population, and could be used as an alternative to molecular methods to individualise isoniazid therapy in our high tuberculosis burden setting." (PMID 33392048, 2020). "Isoniazid, a first line drug in tuberculosis (TB) treatment is metabolized by the NAT2 enzyme." (PMID 30452466, 2018). "The phase II enzyme N-acetyltransferase 2 (NAT2) has only a minor role in drug metabolism generally but a key role in metabolism of isoniazid, an important drug in the treatment of tuberculosis (TB), which is usually used in combination with other drugs." (PMID 28028769, 2017). "Following the initiation of tuberculosis treatment within 1–7 days, the detection of NAT2 demethylation index proved to be considerably more effective in distinguishing ATDILI patients from non-ATIDLI patients in tuberculosis patients, compared to ALT and AST." (PMID 40133601, 2025). "Besides this, our in-depth analysis revealed a strong relationship between a lower NAT2 demethylation index and an increased occurrence of ATDILI in tuberculosis patients." (PMID 40133601, 2025). "NAT2 promoter methylation in blood leukocyte of 102 tuberculosis patients (49 ATDILI cases and 53 non-ATDILI cases) and 100 healthy controls were quantified using quantitative real-time methylation-specific polymerase chain reaction." (PMID 40133601, 2025). "The plasma concentration of INH is influenced by several variables, which encompass severity of tuberculosis, comorbidities like HIV coinfection, concurrent food intake, N-acetyltransferase 2 (NAT2) acetylation phenotypes, and the quality of the dispensed medication." (PMID 37878973, 2023).
tuberculosis (continued). "One of the well-studied phase II drug metabolizing enzymes is N-acetyltransferase 2 (NAT2) which has an essential role in the detoxification and metabolism of several environmental toxicants and many therapeutic drugs like isoniazid (antituberculosis, TB) and antimicrobial sulfonamides." (PMID 32626768, 2020). "The PBPK model for oral administration was therefore coupled with a pharmacodynamic (PD) model of mycobacterial growth in human lungs to analyze the influence of the NAT2 phenotype, INH dose, and administration intervals on the efficacy and toxicity of INH-based tuberculosis treatment." (PMID 27480867, 2016). "Comparisons of CYP2B6, CYP3A5, NAT2, SLCO1B1 and ABCB1 variant alleles and genotype/haplotypes between DILI non-DILI cases among HIV patients with or without tuberculosis." (PMID 22808112, 2012). "In addition to NAT2, it appears that CYP2E1 and solute carrier organic anion transporter family member 1B1(OATP1B1) coded for by SLCO1B1 gene, could also be important biomarkers for isoniazid-induced liver toxicity in adult patients with tuberculosis." (PMID 26402689, 2015). "ROC curve analysis revealed that NAT2 demethylation index was more sensitive and specific in distinguishing ATDILI cases from non-ATDILI cases compared to serum aminotransferases in tuberculosis patients within 1–7 days of treatment initiation." (PMID 40133601, 2025). "In comparison to tuberculosis patients without ATDILI, patients with ATDILI had a significant decrease in NAT2 demethylation index (P < 0.0001)." (PMID 40133601, 2025).
bladder cancer (46 papers, 1999 to 2026). "Previous research has identified the N-acetyltransferase (NAT2) gene as being associated with bladder cancer risk." (PMID 40510732, 2025). "Previous studies have observed an interaction between NAT2 and smoking in relation to bladder cancer risk." (PMID 39898788, 2025). "Interactions between cigarette smoking (as the major risk of bladder cancer) and N-acetyl transferase 2 (NAT2) and Glutathione-s-transferaseM1 (GSTM1) variants, the two best-known candidates, have been consistently associated with BC development." (PMID 37686494, 2023). "The statement indicating a higher risk of bladder cancer in women using hair dyes, especially those containing permanent dyes, in association with the N-acetyltransferase-2 (NAT2) slow acetylation phenotype." (PMID 38283839, 2023). "From the example of bladder cancer risk, the OR for the association between NAT-2 genetic polymorphism status (X) and cigarette smoking status (Z) among cases was calculated." (PMID 37152190, 2022). "Smoking has shown interactions with bladder cancer (BC) genetic variants, especially N‐acetyltransferase‐2 (NAT2), a tobacco smoke metabolism gene, on BC risk." (PMID 35285182, 2022). "Previous studies have suggested that the rapid-acetylator genotype of NAT2 leads to an increased risk of various types of cancer, particularly leukemia, colorectal and bladder cancer." (PMID 33072605, 2020). "It has been proposed that polymorphisms in members of GST of carcinogen-detoxifying gene family as well as in NAT2 confer increased risk of bladder cancer." (PMID 31646988, 2019). "When analyzing 12 susceptible loci in relation to bladder cancer, two most notably showed significant additive gene-environment interactions: NAT2 (P = 7×10-4) and UGT1A6 (P = 8×10-4)." (PMID 27690298, 2017). "The NAT2 polymorphism leads to three genotypes of acetylation, including slow acetylators, more sensitive at risk of bladder cancer in exposure to aromatic amines." (PMID 28929116, 2017). "Epidemiological studies and genome-wide association (GWA) studies in Europe consistently reported higher risk of bladder cancer associated with the SNP-inferred NAT2 slow acetylation status among ever smokers." (PMID 27223070, 2016). "Epidemiological studies in Europe and United States, especially those among smokers, have reported associations between SNP-inferred NAT2 slow acetylation status and increased risk of bladder cancer." (PMID 27223070, 2016). "In summary, this study demonstrates a statistically significant reduced risk of bladder cancer associated with the SNP-inferred NAT2 slow acetylation status, but an increased risk of bladder cancer with the CMR-determined slow acetylation status." (PMID 27223070, 2016). "There are few reports that examined the association between NAT2 acetylation status and bladder cancer risk among Asian populations." (PMID 27223070, 2016). "NAT2 slow acetylation status is significantly associated with increased bladder cancer risk among European populations, but its association in Asian populations is inconclusive." (PMID 27223070, 2016). "It was reported that partial linkage disequilibrium exists between the NAT1*10 allele and the NAT2 fast acetylation genotype, and a reduced risk for bladder cancer was identified in carriers of these co-existing genotypes." (PMID 25413361, 2014). "It is well established that a deletion variant of the detoxifying phase II metabolizing enzyme glutathione S-transferase M1 (GSTM1), in addition to N-acetyltransferase 2 (NAT2) slow acetylation are associated with increased urinary bladder cancer risk." (PMID 23284801, 2012). "For bladder cancer, in which N-acetylation is a detoxification step, NAT2 slow acetylator phenotype presents a higher risk." (PMID 22238607, 2012). "It is unlikely that the aromatic amine substrates for NAT2, found in tobacco products and linked with bladder cancer, are present in the DBP mixture." (PMID 20675267, 2010).
bladder cancer (continued). "The associations with bladder cancer risk for NAT2 slow versus rapid/intermediate acetylator and GSTM1 null versus present within each THM stratum were variable and consistent with the overall elevated main effects for these genes." (PMID 20675267, 2010). "They found a significant interaction between NAT2 and the number of cigarettes per day in bladder cancer risk by case-only analysis, while the risk estimate for GSTM1 was not modified by ethnicity nor by smoking intensity." (PMID 22275976, 2008). "Specifically, the GSTM1 null genotype increases the overall risk of bladder cancer; while the NAT2 slow acetylator genotype appears to increase risk particularly among cigarette smokers." (PMID 17319747, 2007). "We evaluated interactions between the VEGF SNPs significantly associated with bladder cancer risk and other determinants of risk (i.e., age, gender, smoking status, family history of cancer in at least one first-degree relative, and NAT2 and GSTM1 genotypes)." (PMID 17319747, 2007). "Our data suggest an association between the NAT2 slow acetylation genotype and increased bladder cancer risk in female smokers." (PMID 17026750, 2006). "In summary, these prospective results are consistent with previous literature supporting associations between bladder cancer and the NAT2 slow acetylation and the GSTM1 null genotypes." (PMID 17026750, 2006). "This article reviews the results of 21 published case–control studies of NAT2 polymorphism and bladder-cancer risk, with a total of 2700 cases and 3426 controls." (PMID 10917561, 2000). "There was insufficient evidence to assess the joint effect of NAT2 and occupational exposure to arylamines on bladder cancer risk." (PMID 10917561, 2000). "Some studies indicate that specific gene variations in GSTM-1 and NAT-2, which are involved in detoxifying carcinogens, could potentially increase the susceptibility of certain individuals to bladder cancer." (PMID 37762677, 2023). "Indeed, studies have shown a higher relative risk of bladder cancer due to smoking for NAT2 slow acetylators compared to NAT2 rapid/intermediate acetylators." (PMID 37686494, 2023). "Additionally, studies have reported a higher risk of bladder cancer in women who use hair dyes containing permanent dyes, with women with a higher risk for the N-acetyltransferase-2 slow acetylation phenotype." (PMID 38283839, 2023). "Notably, individuals with a slow NAT2 acetylator genotype were identified as a significant risk group for bladder cancer, particularly among smokers (HR: 1.31; 95% CI, 1.01–1.70)." (PMID 37762677, 2023). "In the underlying population from which cases arise, two risk factors (e.g., the NAT-2 genetic polymorphism and cigarette smoking) may interact to affect the odds of an outcome (e.g., bladder cancer)." (PMID 37152190, 2022). "For example, X may represent a gene (e.g., NAT-2) that modifies the effect of an environmental or behavioral risk factor, Z (e.g., smoking) on disease risk (e.g., bladder cancer)." (PMID 37152190, 2022). "Interestingly, a genetic predisposition to bladder cancer has been previously reported, involving genes that control carcinogen metabolism, such as N-acetyltransferase 2 (NAT2)." (PMID 30875794, 2019). "The adjustment for CMR resulted in significant strengthening of the association, which indirectly demonstrated an important role of O-acetylation in the activation of bladder carcinogens, leading to elevated risk of bladder cancer for individuals who carried high functional alleles of the NAT2 gene." (PMID 27223070, 2016). "However, additional large investigations of bladder cancer risk, NAT2 genetic variation and comprehensive assessment of smoking habits, notably flue- or air-cured tobacco, are still needed to further assess this interaction." (PMID 27809812, 2016).
bladder cancer (continued). "Conversely, the effect of CMR-determined slow acetylation status on bladder cancer risk was greatly increased after controlling for genetic variation in the NAT2, further suggesting hepatic N-acetylation measured by CMR is a detoxification pathway of bladder carcinogen arylamines." (PMID 27223070, 2016). "Therefore, the net effect of SNP-inferred NAT2 acetylation status on risk of bladder cancer would depend on the individual's exposure to specific type of bladder carcinogens." (PMID 27223070, 2016). "Thus, if carcinogens in tobacco smoke where implicated in MPNs, as they are in bladder cancer, then we should have detected the main effect of NAT2 in our study." (PMID 25719551, 2015). "The strong enrichment signal left in this pathway even after the removal of the UGT1A and NAT2 genes from the analysis indicates that other genetic variations affecting aromatic amines detoxification may contribute to bladder cancer susceptibility." (PMID 22238607, 2012). "Notably, the risk of bladder cancer associated with NAT2 slow acetylation genotype is restricted to smokers." (PMID 22238607, 2012). "Colon and bladder cancers have been associated with NAT2 acetylation status." (PMID 22238607, 2012). "However, DBP mixtures are complex, and we felt it worthwhile to evaluate the possibility of an interaction between DBPs and slow/rapid acetylation genotypes of NAT2 in risk of bladder cancer." (PMID 20675267, 2010). "The slow NAT2 acetylation genotype compromises its detoxification ability, and studies have consistently observed an association between the slow NAT2 genotype and increased bladder cancer risk." (PMID 17026750, 2006). "Given their biological role, polymorphisms within the GSTT1, GSTM1, NAT1, and NAT2 genes may be important in determining an individual's susceptibility to bladder cancer." (PMID 17026750, 2006). "In summary, our data support the prior evidence that the GSTM1 null genotype and the NAT2 slow acetylation genotype may affect an individual's bladder cancer risk." (PMID 17026750, 2006). "These compounds may be partially responsible for the increased bladder cancer risk observed among slow NAT2 acetylators who have a decreased capacity to detoxify aromatic amines." (PMID 17026750, 2006). "The published evidence suggests that NAT2 slow acetylator phenotype or genotype may be associated with a small increase in bladder cancer risk." (PMID 10917561, 2000). "Genetic polymorphism of the carcinogen metabolizing enzyme N -acetyl transferase 2 (NAT2) may influence susceptibility to bladder cancers related to smoking or to occupational exposure to arylamine carcinogens." (PMID 10917561, 2000). "The results are consistent with the hypothesis that NAT1 and NAT2 might modulate the susceptibility to bladder cancer associated with cigarette smoking." (PMID 10507782, 1999). "Reduced NAT2 activity has been associated with increased susceptibility to certain diseases, such as systemic lupus erythematosus, some types of cancer (hepatocellular carcinoma, bladder cancer, etc.)and increased toxicity to some drugs, such as isoniazid and hydralazine." (PMID 38927494, 2024). "Therefore, NAT2 SNP-inferred slow acetylation status potentially measured variations in both N- and O-acetylation catalytic capacities, and was associated with decreased risk of bladder cancer in our study." (PMID 27223070, 2016). "Also, a recent study from New England found that women who used permanent dyes and had a college degree had an increased risk of bladder cancer and that the risk was more pronounced among exclusive users of permanent hair dyes who also had the NAT2 slow acetylation phenotype." (PMID 22581032, 2012). "A case–control study from California found an increased risk of bladder cancer in long-term (15 years and more) users of permanent hair dyes among women, which was more pronounced among exclusive users and women with the N-acetyltransferase-2 (NAT2) slow acetylator phenotype." (PMID 22581032, 2012).